IGF2BP2 (insulin like growth factor 2 mRNA binding protein 2)
Description:
RNA-binding factor that recruits target transcripts to cytoplasmic protein-RNA complexes (mRNPs). This transcript 'caging' into mRNPs allows mRNA transport and transient storage. It also modulates the rate and location at which target transcripts encounter the translational apparatus and shields them from endonuclease attacks or microRNA-mediated degradation (By similarity). Preferentially binds to N6-methyladenosine (m6A)-containing mRNAs and increases their stability. Binds to the 5'-UTR of the insulin-like growth factor 2 (IGF2) mRNAs. Binding is isoform-specific. Binds to beta-actin/ACTB and MYC transcripts. Increases MYC mRNA stability by binding to the coding region instability determinant (CRD) and binding is enhanced by m6A-modification of the CRD.
Synonyms: IMP-2; IMP2; VICKZ2; p62
Tractability: PROTAC: ubiquitination databases record sites on it; its protein half-life has been measured.
Gene: Protein-coding gene on chromosome 3 (185,643,130 to 185,825,061, reverse strand). Ensembl gene ENSG00000073792.
Subcellular location: Nucleus; Cytoplasm; Cytoplasm, P-body; Cytoplasm, Stress granule
Subcellular location (Human Protein Atlas): Cytosol
Pathways (Reactome):
Metabolism of RNA: Insulin-like Growth Factor-2 mRNA Binding Proteins (IGF2BPs/IMPs/VICKZs) bind RNA
Gene Ontology:
Molecular function: mRNA 3'-UTR binding; mRNA 5'-UTR binding; N6-methyladenosine-containing RNA reader activity; protein binding; RNA binding; translation regulator activity; nucleic acid binding
Biological process: CRD-mediated mRNA stabilization; RNA stabilization; anatomical structure morphogenesis; negative regulation of translation; nervous system development; regulation of cytokine production
Cellular component: cytoplasm; cytoplasmic stress granule; cytoskeleton; cytosol; nucleus; P-body
Genetic constraint (gnomAD): Loss-of-function variants: 12 observed, 59.76 expected, observed/expected ratio (o/e) 0.2, 90% interval 0.13 to 0.32. The upper end of that interval is the gene's LOEUF score, 0.32, which puts it in group 1 of 6, group 1 being the genes least tolerant of losing a copy. Missense variants: 492 observed, 712.89 expected, observed/expected ratio (o/e) 0.69, 90% interval 0.64 to 0.74. Synonymous variants: 273 observed, 278.15 expected, observed/expected ratio (o/e) 0.98, 90% interval 0.89 to 1.09.
Homologues: Orthologues: chimpanzee IGF2BP2 (100% identical), pig IGF2BP2 (99% identical), rabbit IGF2BP2 (98% identical), rat Igf2bp2 (95% identical), mouse Igf2bp2 (95% identical), macaque IGF2BP2 (93% identical), guinea pig IGF2BP2 (88% identical), dog IGF2BP2 (81% identical), zebrafish igf2bp2a (78% identical), zebrafish igf2bp2b (52% identical), Drosophila melanogaster Imp (34% identical), Caenorhabditis elegans imph-1 (28% identical), and 6 more. Paralogues in human: IGF2BP1 (65% identical), IGF2BP3 (64% identical), KHSRP (20% identical), FUBP1 (19% identical), PCBP3 (18% identical), PCBP2 (18% identical), FUBP3 (17% identical), PCBP1 (17% identical), PCBP4 (17% identical), HNRNPK (15% identical), NOVA2 (14% identical), NOVA1 (14% identical).
Diseases named in the same sentence as IGF2BP2 in open-access papers:
IGF2BP2 is named in the same sentence as 200 diseases in open-access papers, as found by Europe PMC text mining. Sharing a sentence is not in itself a finding about the gene and the disease. The quoted sentences say what the papers report.
colorectal cancer (133 papers, 2010 to 2025). A primary or metastatic malignant neoplasm that affects the colon or rectum. "It has been reported that IGF2BP2 is associated with the development of glioblastoma, colorectal cancer, breast cancer, non-small-cell lung cancer, and pancreatic cancer." (PMID 36358799, 2022). "LncRNA LINRIS was upregulated in colorectal cancer tissues and associated with the poor overall survival and aerobic glycolysis of colorectal cancer patients by stabilizing IGF2BP2." (PMID 35676619, 2022). "IGF2BP2, belonging to a conserved family of RBPs, is associated with a large number of diseases, including diabetes, acute myelocytic leukaemia, and colorectal carcinoma, for its abnormal energy expenditure and life span in pathological conditions." (PMID 35293050, 2022). "This hints that the IGF2BP2/TUG1 axis is an underlying target for colorectal cancer treatment." (PMID 35014946, 2022). "As a reader of m6A, IGF2BP2 is associated with carcinogenesis, and has been tested to be associated with the occurrence and prognosis of various cancers including colorectal cancer, gastrointestinal cancer, endometrial cancer, pancreas cancer, breast cancer and Head and Neck Squamous Cell Carcinoma." (PMID 34705667, 2021). "In colorectal cancer, knockdown of IGF2BP2 attenuates MYC-mediated glycolysis in colorectal cancer cells, and the LINRIS–IGF2BP2–MYC axis is a promising therapeutic target for colorectal cancer." (PMID 40469197, 2025). "Down-regulated FTO and ALKBH5 co-operatively activate FOXO signaling through m6A methylation modification in HK2 mRNA mediated by IGF2BP2 to enhance glycolysis in colorectal cancer." (PMID 40428320, 2025). "For example, circEZH2/IGF2BP2 enhances the stability of CREB1 mRNA to promote the progression of colorectal cancer." (PMID 40612865, 2025). "Its abnormal expression is associated with cancer development, and elevated levels of IGF2BP2 in pancreatic cancer, colorectal cancer, or esophageal squamous cell carcinoma have been linked to poor prognostic outcomes." (PMID 40597017, 2025). "The oncogenic role of long intergenic noncoding RNA for IGF2BP2 stability (LINRIS) has been reported in colorectal cancer." (PMID 39381424, 2024). "It had been reported that IGF2BP2 overexpression aggravated cell proliferation in colorectal cancer and hepatocellular carcinoma." (PMID 39014364, 2024). "In colorectal cancer, IGF2BP2 enhances the ZFAS1-OLA1 axis and promotes cell proliferation and the Warburg effect." (PMID 38560499, 2024). "IGF2BP2 contributed to colorectal cancer pathogenesis and progression by SOX2 m6A methylation and preventing its degradation." (PMID 38714753, 2024). "A similar observation has been reported regarding IGF2BP2 increasing cisplatin resistance in colorectal cancer." (PMID 38665783, 2024). "In colorectal cancer, IGF2BP2 and IGF2BP3 can stimulate vasculogenic mimicry formation by separately stabilizing the transcripts of EphA2 and VEGF via interaction with their m6A sites." (PMID 37280679, 2023). "In CRC cells, METTL3 is an oncogene that stabilizes HK2 as well as GLUT1 expression via IGF2BP2- or IGF2BP2/3-related mechanisms and activates the subsequent aerobic glycolysis pathway to boost colorectal cancer progression." (PMID 37055798, 2023). "LINC00460/DHX9/IGF2BP2 complex stimulates colorectal cancer proliferation and metastasis by interacting with IGF2BP2 and regulating HMGA1 mRNA stability by m6A modification." (PMID 37744330, 2023). "Upregulated IGF2BP2 is significantly correlated with weak prognosis, providing a hopeful predictor for pancreatic cancer, colorectal cancer, osteosarcoma, and lung adenocarcinoma." (PMID 37280679, 2023). "Increased MTA1 regulating colorectal cancer metastasis relies on FTO/IGF2BP2 regulated m6A methylation." (PMID 37280679, 2023). "In colorectal cancer, IGF2BP2 stabilizes lncRNA ZFAS1 in an m6A-dependent manner, which activates OLA1 to reinforce adenosine triphosphate (ATP) hydrolysis and aerobic glycolysis." (PMID 37280679, 2023).
colorectal cancer (continued). "CircEZH2/miR-133b/insulin like growth factor 2 mRNA binding protein 2 (IGF2BP2) aggravates colorectal cancer progression via enhancing the stability of m6A-modified CREB1 mRNA." (PMID 38023219, 2023). "The long non-coding RNA LINRIS boosted glycolysis and malignant progression in colorectal cancer through the IGF2BP2-c-Myc axis." (PMID 37932821, 2023). "To summarize, our study has figured out the oncogenic function of IGF2BP2-stabilized TUG1 in colorectal cancer." (PMID 35014946, 2022). "Specifically, metastasis and colony formation of colorectal cancer cells can be accomplished by upregulating IGF2BP2 to stabilize the ZFAS1/OLA1 axis, leading to increased ATP hydrolysis and glycolysis and activation of the Warburg effect." (PMID 35794625, 2022). "In colorectal cancer, IGF2BP2 regulates cancer cells glycolysis by controlling hexokinase and glucose transporter 1 expression." (PMID 35915142, 2022). "In colorectal cancer, IGF2BP2 directly binds to the m6A sites of lncRNA ZFAS1 and increases its stability to activate the Warburg effect." (PMID 35541906, 2022). "Analogously, in colorectal cancer, IGF2BP2 recognizes and binds to m6A-modified YAP and enhances the stability of YAP mRNA, thereby facilitating tumorigenesis." (PMID 35541906, 2022). "The lncRNA LINRIS interacts with IGF2BP2 to maintain the stability of IGF2BP2, and promote the progression of colorectal cancer." (PMID 35410446, 2022). "For instance, IGF2BP2 promotes colorectal cancer cell proliferation and survival via disturbing RAF-1 degradation by miR-195." (PMID 36257938, 2022). "The knockdown of lncRNA LINRIS was reported to attenuate MYC-mediated aerobic glycolysis downstream of IGF2BP2 in colorectal cancer cells." (PMID 35002506, 2022). "IGF2BP2 was reported by a previously published study to encourage the metastasis of colorectal cancer." (PMID 36358799, 2022). "IGF2BP2 binds to the m6A site of Myc mRNA, enhancing Myc axis-mediated glycolysis and promoting colorectal cancer cell proliferation." (PMID 35936671, 2022). "It has been reported that the lncRNA and m6A methylation recognition protein “reader” IGF2BP2 plays a role in the proliferation and metabolism of colorectal cancer." (PMID 35936671, 2022). "To evaluate the expression features of lncRNA-TUG1 and IGF2BP2 in colorectal cancer, we carried out qRT-PCR and Western blot." (PMID 35014946, 2022). "For example, the m6A modification of circNSUN2 increases its export to the cytoplasm and circNSUN2 enhances the stability of HMGA2 mRNA to promote colorectal carcinoma metastasis progression, forming a circNSUN2/IGF2BP2/HMGA2 RNA-protein ternary complex." (PMID 35999496, 2022). "Among these m6A regulators, IGF2BP2 had been proven to be a downstream m6A reader of SOX2 in colorectal carcinoma." (PMID 35558067, 2022). "The over-expressed miR-216b restrained the cell proliferation, migration and invasion in HCC through the HBx-miRNA-216b-IGF2BP2 signaling pathway, a similar phenomenon was observed in colorectal cancer via targeting SRPK1." (PMID 34338136, 2021). "IGF2BP2 is reported to facilitate cell proliferation, migration, and angiogenesis in human cancer cells, like colorectal cancer and lung cancer cell lines." (PMID 34753397, 2021). "According to previous reports, including work in our group, IGF2BP2 facilitated colorectal cancer progression, and our current findings provide another line of evidence supporting its characterization as an oncogene." (PMID 34218271, 2021). "There is experimental evidence that IGF2BP2 can promote the metastasis of colorectal cancer through the formation of circNSUN2/IGF2BP2/HMGA2 protein ternary complex in the cytoplasm." (PMID 33952279, 2021). "LINRIS was proven to promote carcinogenesis of colorectal cancer by serving as a stabilizer of IGF2BP2 (reader)." (PMID 34238292, 2021).
colorectal cancer (continued). "Another lncRNA, long intergenic noncoding RNA for IGF2BP2 stability, suppresses the degradation of IGF2BP2 by inhibiting the ubiquitination–autophagy pathway, leading to glycolysis upregulation in colorectal cancer." (PMID 33627136, 2021). "This confirms the potential of LINRIS-IGF2BP2-MYC axis for colorectal cancer targeted therapy; LncRNA LINC00460 interacts with IGF2BP2 and DHX9 to form the LINC00460/DHX9/IGF2BP2 complex." (PMID 35070987, 2021). "Overexpression of IGF2BP2 has been indicated to be related to poor survival of patients with colorectal cancer, acute myelocytic leukemia and metaplastic breast cancer." (PMID 32514248, 2020). "This is consistent with previous studies of IGF2BP2 in cancers, including colorectal cancer, gastrointestinal cancer, endometrial cancer, pancreas cancer, breast cancer, and hepatic carcinoma." (PMID 32391379, 2020). "IGF2BP2 overexpression was observed in pancreatic cancer, colorectal cancer, and SCCHN, which promoted cancer cell proliferation by activating the PI3K/Akt signaling pathway." (PMID 33505420, 2020). "Conversely, insulin-like growth factor 2 mRNA-binding protein 2 (IGF2BP2) was found to be downregulated in colorectal cancer." (PMID 32973402, 2020). "At present, IGF2BP2 has been identified as a novel stage-specific biomarker of colorectal cancer progression." (PMID 32391379, 2020). "Among 83 serum samples from 48 gastric, 10 esophageal, and 25 large intestine cancer patients analyzed, 32 were detected with IGF2BP2 autoantibody." (PMID 29736175, 2018). "For example, lncRNA Long Intergenic Non‐coding RNA for IGF2BP2 Stability (LINRIS) blocks K139 ubiquitination of Insulin‐like Growth Factor 2 mRNA‐Binding Protein 2 (IGF2BP2) and stabilizes IGF2BP2 protein to control aerobic glycolysis in colorectal cancer cells and promote this cancer growth." (PMID 40231344, 2025). "Furthermore, IGF2BP2 is involved in immune responses in colorectal cancer and can induce macrophages from M1 type to M2 type (the latter having pro-tumor activity) in ovarian cancer." (PMID 40088376, 2025). "The lncRNA 00460/IGF2BP2 complex May promote colorectal cancer cell proliferation by mediating high mobility group AT-hook 1 (HMGA1) transcript stability through METTL3-dependent m6A modification." (PMID 40986143, 2025). "For example, IGF2BP2 expression in colorectal cancer is influenced by DNA methylation." (PMID 40088376, 2025). "IGF2BP2 regulates disease progression, including acute myeloid leukemia and colorectal cancer." (PMID 40727611, 2025). "ZBTB48 ablation also accelerates growth of HCT-116 colorectal cancer cells and modulates FTO-dependent regulation of Metastasis-associated protein 1 (MTA1) transcripts by controlling the binding to MTA1 mRNA of the m6A reader IGF2BP2." (PMID 39300486, 2024). "Notably, previous studies have implicated IGF2BP2 in modulating the TME through macrophage polarization and immune cell function in other cancers, such as colorectal cancer." (PMID 39711402, 2024). "Studies have found that B3GNT6 is closely related to a variety of disease processes, such as immunity deficiency, colorectal cancer and m6A modification, Together, these results indicate that B3GNT6 may be the downstream target of IGF2BP2." (PMID 35908253, 2023). "IGF2BP2 also can enhance colorectal cancer cell glycolysis through the downstream MYC gene." (PMID 37280679, 2023). "In addition, lncRNAs have a positive effect on aerobic glycolysis in colorectal cancer, which is achieved by stabilizing IGF2BP2." (PMID 37910780, 2023). "This may affect the biological function of circRNAs, such as m6A modification of circNSUN2 could promote the liver metastasis of colorectal cancer by forming a circNSUN2/IGF2BP2/HMGA2 RNA-protein ternary complex." (PMID 37658417, 2023). "It has been reported IGF2BP2 could facilitate colorectal cancer cell proliferation by inhibiting the degradation of replication factor A protein 1 (RFA1)." (PMID 37936610, 2023).
colorectal cancer (continued). "Moreover, the long non-coding (lnc)RNA LINRIS stimulates aerobic glycolysis in colorectal cancer (COAD) by stabilizing IGF2BP2 via the inhibition of IGF2BP2 K139 ubiquitination." (PMID 36686749, 2022). "In addition, lncRNA LINRIS stabilizes IGF2BP2 by blocking its ubiquitination to promote the c-MYC-driven glycolysis in colorectal cancer." (PMID 35541906, 2022). "Moreover, LINC00460 was found to interact with IGF2BP2 in promoting the proliferation and metastasis of colorectal cancer by increasing the stability of HMGA1 mRNA via an m6A-mediated modification." (PMID 36438499, 2022). "In addition, LncRNA 91H regulates the migration and invasion of colorectal cancer cells by interacting with IGF2BP2." (PMID 34630126, 2021). "For example, LncRNA LINRIS promotes colorectal cancer cell proliferation by stabilizing IGF2BP2." (PMID 34630126, 2021). "The m6A “reader” YTH protein family and IGF2BP2 have been widely reported in colorectal cancer, and therefore it is reasonable to speculate that the m6A “reader” may play an important role in the progression of colorectal cancer, which deserves deeply study." (PMID 35004679, 2021). "LncRNA LINRIS can stabilize IGF2BP2 and promote aerobic glycolysis in colorectal cancer." (PMID 34917609, 2021). "Furthermore, IGF2BP2 exhibited pro-proliferation role in dental pulp cells and colorectal cancer cells." (PMID 34753397, 2021). "It has been previously reported that circNSUN2 could enhance the stability of HMGA2 mRNA to promote colorectal carcinoma metastasis progression by forming a circNSUN2/IGF2BP2/HMGA2 RNA-protein ternary complex in the cytoplasm." (PMID 33853613, 2021). "Analysis from our in vitro and clinical experiments has demonstrated that many transcripts exist in sense:antisense pairs including IGF2BP2, which may have a direct regulatory function in the context of colorectal cancer." (PMID 21172019, 2010). "In colorectal carcinoma (CRC), IGF2BP2 binds the 3' untranslated region (3' UTR) of HMGA1, augmenting its stability and driving tumor growth and metastasis." (PMID 41041073, 2025). "Also, the accumulation of IGF2BP2 could activate the RhoA/Rock pathway, which in turn promoted M2 macrophage polarization and accelerated colorectal cancer progression." (PMID 39014364, 2024). "For example, knockdown of the lncRNA LINRIS in colorectal cancer blocks K139 ubiquitination of IGF2BP2 (a m6A reader), preventing its degradation by the autophagic lysosomal pathway and ultimately, attenuating the downstream pathways of IGF2BP2, such as MYC-mediated glycolysis in tumor cells." (PMID 35794625, 2022). "Modified IGF2BP2 participates in the development and progression of multiple metabolic disease and cancers, including diabetes, obesity, fatty liver, breast cancer, colorectal carcinoma, esophageal adenocarcinoma, glioma, hepatocellular carcinoma, lung cancer, pancreatic cancer and many others." (PMID 33568150, 2021). "For example, in colorectal cancer, METTL14 inhibits the proliferation, metastasis and invasion of tumor cells either by enhancing the expression of KLF4 in IGF2BP2-m6A manner, or by inhibiting YTHDF2-mediated SOX472, or by suppressing XIST." (PMID 40734692, 2025). "In colorectal cancer, METTL3, as an oncogene, maintains the stable expression of SOX2 through the m6A IGF2Bp2‐dependent mechanism in CRC cells." (PMID 40919129, 2025). "Three different studies identify different m6A-dependent mechanisms and related target gene mRNAs such as IGF2BP2-stabilized SOX2, IGF2BP1-stabilized CBX8, and IGF2BP2/3-stabilized HK2 and SLC2A1 in colorectal cancer cells." (PMID 40734692, 2025). "In colorectal cancer, METTL3 methylates SOX2 mRNA, allowing it to bind to the mRNA-binding protein IGF2BP2 at m6A sites, preventing SOX2 mRNA degradation and promoting protein expression." (PMID 38238831, 2024).